TCF4 (transcription factor 4)
Diseases named in the same sentence as TCF4 in open-access papers (continued):
Sharing a sentence is not in itself a finding about the gene and the disease.
acute kidney injury (2 papers, 2020 to 2023). Sudden and sustained deterioration of the kidney function characterized by decreased glomerular filtration rate, increased serum creatinine or oliguria. "Another study on miR-155 shows that by regulating the TCF4/Wnt/β-catenin pathway, acute kidney injury can be reduced." (PMID 32596306, 2020). "Besides, Antagonists targeting miR‐106b‐5p attenuate acute kidney injury by upregulating TCF4 to modulate renal function, apoptosis, and autophagy." (PMID 37471571, 2023).
cognitive decline (2 papers, 2015 to 2016). "Also, the absence of early cognitive decline in the adult individuals suggests that TCF4 dysfunction is most detrimental during early brain development." (PMID 27179618, 2016).
colorectal adenocarcinoma (2 papers, 2009 to 2019). The most common type of colorectal carcinoma. "Although all of these cells increased expression of TCF4 in response to vitamin D we chose to use the human colorectal adenocarcinoma cell line, CaCo2 for several reasons." (PMID 19924301, 2009).
corneal edema (2 papers, 2021). "In view of the suggested contribution of TCF4 sequence variants to the pathogenesis of FECD in terms of susceptibility to oxidative stress and cell adhesion, this is the first study to investigate whether the CTG expansion load contributes to time to resolution of corneal edema after DSO." (PMID 34698281, 2021).
cutaneous melanoma (2 papers, 2023 to 2024). A primary melanoma arising from atypical melanocytes in the skin. "Using a Venn diagram with TCF-4 co-expressed genes versus CDH5 co-expressed genes, 7 genes were robustly correlated, being S1PR1 the most prominent one not only in uveal melanoma but also in cutaneous melanoma." (PMID 36797281, 2023).
cystic fibrosis (2 papers, 2017 to 2021). Autosomal recessive disorder caused by pathogenic variants in the CFTR gene (cystic fibrosis transmembrane conductance regulator), which encodes a chloride and bicarbonate channel expressed in epithelial cells, and follow the diagnosis criteria. "Therefore, low expression of Tcf4 (as it occurs in cystic fibrosis) might lead to low transcription of the CFTR gene and high miR-145-5p dependent down modulation of CFTR mRNA." (PMID 29286300, 2017).
Ewing sarcoma (2 papers, 2020 to 2025). A small round cell tumor that lacks morphologic, immunohistochemical, and electron microscopic evidence of neuroectodermal differentiation. "Consistent with mRNA expression, silencing EWS-FLI1 decreased protein level of KLF15, NKX2-2 and TCF4 in Ewing sarcoma cell lines." (PMID 33080033, 2020). "Expression of DOX-inducible shRNAs against either KLF15 or TCF4 potently inhibited xenograft growth of Ewing sarcoma." (PMID 33080033, 2020). "In Ewing sarcoma, a CRC including KLF15, TCF4, and NKX2-2 MTFs that cooperate with EWSR1::FLI1 was reported in A-673 and EW-8 cells." (PMID 41444391, 2025). "Phenotypically, similar to CRC factors in other cancer types, KLF15, TCF4 and NKX2-2 each shows strong pro-growth and pro-survival functions in Ewing sarcoma." (PMID 33080033, 2020). "On the other hand, RREB1-silencing did not produce these co-regulatory effects, demonstrating that in Ewing sarcoma cells, KLF15, TCF4 and NKX2-2 together constitute an inter-connected circuitry." (PMID 33080033, 2020). "Considering the prominent roles of CRC in controlling transcriptional network, we postulated that KLF15, TCF4 and NKX2-2 are required for the viability and proliferation of Ewing sarcoma cells." (PMID 33080033, 2020). "Formed by KLF15, TCF4 and NKX2-2, this CRC apparatus coordinates the gene expression programs, including lipid metabolism, PI3K/AKT and MAPK signaling pathways, in Ewing sarcoma cells." (PMID 33080033, 2020). "In fact, the shared changes account for almost half of all changes in every RNA-Seq of CRC TFs, strongly suggesting that KLF15, TCF4 and NKX2-2 coordinate to regulate the transcriptome of Ewing sarcoma cells." (PMID 33080033, 2020). "This is plausible given that KLF15 almost always cooperates with TCF4 and NKX2-2 in Ewing sarcoma in terms of genomic binding." (PMID 33080033, 2020). "Here, we identify and functionally validate a CRC ‘trio’ constituted by three transcription factors (TFs): KLF15, TCF4 and NKX2-2, in Ewing sarcoma cells." (PMID 33080033, 2020). "A CRC comprising TCF4, NKX2-2, and KLF15 was previously reported in Ewing sarcoma." (PMID 41444391, 2025). "In order to address this hypothesis, we modified a computational algorithm given the central role of EWS-FLI1, and identified a CRC ‘trio’ constituted by KLF15, TCF4 and NKX2-2 in Ewing sarcoma cells." (PMID 33080033, 2020). "Taken together, these results demonstrate that as CRC members, KLF15, TCF4 and NKX2-2 may positively co-regulate each other and promote the growth and survival of Ewing sarcoma cells." (PMID 33080033, 2020). "Here, we tested the dependency of Ewing sarcoma cells on KLF15 and TCF4 in vivo." (PMID 33080033, 2020). "In addition to cooperating with EWS-FLI1 to co-amplify their own transcription through a CRC model, KLF15, TCF4 and NKX2-2 also exhibit prominent capability of co-regulating the epigenome of Ewing sarcoma cells." (PMID 33080033, 2020). "Taken together, these data demonstrate that KLF15, TCF4 and NKX2-2 coordinately promote the transcription of chief components of the PI3K/AKT and MAPK signaling pathways, thereby activating these pro-growth and pro-survival signaling cascades in Ewing sarcoma." (PMID 33080033, 2020). "Indeed, NKX2-2 has been reported to promoting cell proliferation of Ewing sarcoma, however, the biological significance of either KLF15 or TCF4 had hitherto been unknown in this cancer." (PMID 33080033, 2020). "Indeed, NKX2-2 has been established as a tumor-promoting factor in Ewing sarcoma, but the functions of KLF15 and TCF4 remained hitherto unknown in this cancer." (PMID 33080033, 2020).
gastritis (2 papers, 2022 to 2024). Inflammation of the stomach. "For instance, variants of TCF4 (shared across T2D, GERD, gastritis-duodenitis, and diverticular disease) have been reported in T2D, GERD, and Crohn’s disease." (PMID 38802514, 2024). "Similarly, TCF4 and GPX4 mRNA levels were higher in H. pylori-positive human gastritis samples." (PMID 35534546, 2022).
head and neck cancer (2 papers, 2017). A primary or metastatic malignant neoplasm affecting the head and neck. "More recent studies also suggest that the self-renewal capacity of cancer stem cells in colon and head and neck cancer cells was blocked by perturbation of the interaction between β-catenin and the transcription factor TCF4 in the nucleus." (PMID 28223538, 2017). "Since we demonstrated altered transcriptional activity of TCF4 downstream of mutant PIK3CA in breast and head and neck cancer cells, targeting TCF4 might be new therapeutic strategy in PIK3CA mutant patients." (PMID 28139702, 2017). "Our analysis associated mutant PIK3CA with ELK1 and TCF4 activity in both breast and head and neck cancer, and with FOXO1 activity in BRCA but not in head and neck cancer." (PMID 28139702, 2017).
Hepatic steatosis (2 papers, 2016 to 2023). Steatosis is a term used to denote lipid accumulation within hepatocytes. "In the present study, we demonstrated that the expression levels of nuclear β-catenin and TCF4, the latter of which is a main transcriptional regulator of Wnt signaling, were decreased in an in vitro model of hepatic steatosis." (PMID 27907035, 2016).
hepatoblastoma (2 papers, 2022 to 2023). Hepatoblastoma (HB) is a malignant hepatic tumor and is the most common pediatric liver cancer. "In summary, several independent approaches revealed that the inhibition of the β-catenin-TCF4-CEGRs/ALCDs pathway reduces the proliferation of hepatoblastoma cells." (PMID 36551548, 2022). "In summary, the studies of the ph-S675-β-catenin-TCF4-CEGRs/ALCDs pathway in HBL patients, in hepatoblastoma cell lines HepG2 and Huh6 and in PDX models of HBL, demonstrated the essential role of the ph-S675-β-catenin-TCF4-CEGRs/ALCDs axis in the development of aggressive HBL." (PMID 36551548, 2022).
HIV-1 infection (2 papers, 2020 to 2022). The type species of lentivirus and the etiologic agent of acquired immunodeficiency syndrome (AIDS). "Most studies of Wnt/β-catenin signalling in relation to HIV-1 infection have focused on the regulation of TCF/LEF family member TCF4, which has been identified as a repressor of HIV-1 replication in astrocytes and monocytes." (PMID 34985411, 2022).
hyperglycaemia (2 papers, 2013 to 2022). "Therefore, it is conceivable that hyperglycaemia of NZO mice inhibits the expression of Tcf4 in pMSCs, which could ultimately induce their differentiation to adipocytes." (PMID 35216219, 2022).
insomnia (2 papers, 2021 to 2022). A sleep disorder characterized by difficulty in falling asleep and/or remaining asleep. "We identified 62 variants linked to shared genetics of MDD and insomnia symptoms, with signals near MEIS1, RP11-6N13.1, OLFM4, HEXIM1, and TCF4 being the strongest." (PMID 34680902, 2021). "Another overlapped gene TCF4, shared by three trait pairs (DCC/insomnia, DCC/neuroticism, and DCC/MDD), regulates the expression of cell adhesion molecules to control neuronal positioning during brain development." (PMID 35898629, 2022). "Fifth, our gene-based analysis showed that TCF4 was the only gene that reached genome-wide significance in MDD and insomnia." (PMID 34680902, 2021). "A recent study shows the contribution of TCF4 in mutual influences between MDD and insomnia, which aligns with our result." (PMID 34680902, 2021).
liver fibrosis (2 papers, 2022 to 2024). "Interestingly, the expression of TCF4-sensitive genes appears to be directly related to liver fibrosis, where a higher degree of fibrosis is associated with a stronger effect in human liver." (PMID 35798791, 2022). "The results showed that LECT2 was regulated by β-catenin/TCF4 signaling, thereby regulating angiogenesis and participating in liver fibrosis." (PMID 38881894, 2024). "Considering the link between hepatocyte lipotoxicity and liver fibrosis in NASH prognosis, we subsequently defined the association between TCF4- and MAFK-sensitive genes and human NASH at different stages of fibrosis." (PMID 35798791, 2022). "Moreover, in the context of lipotoxicity, some MAFK and TCF4 target genes were to the corresponding differentially regulated transcripts in human liver fibrosis." (PMID 35798791, 2022).
lupus (2 papers, 2015 to 2021). "Similar to Tlr7-tg, Tcf4 haplodeficiency effectively blocked the development of lupus, as indicated by the significantly reduced anti-DNA antibody levels and glomerulonephritis." (PMID 26528288, 2015). "Although Tcf4 also affects the development of B and T cells as well as a subset of conventional DCs (cDCs), these data nevertheless suggest that pDCs are critically involved in lupus pathogenesis and autoantibody production." (PMID 26528288, 2015). "Intriguingly, they found that both global and DC-specific Tcf4 haplodeficiency abolished splenomegaly and myeloid cell expansion and diminished anti-RNA autoantibody levels in the presence of Tlr7 overexpression, which suggests a profound involvement of pDCs in this lupus model." (PMID 26528288, 2015).
lymph node metastasis (2 papers, 2016 to 2021). "We also found a significant association between patients with lymph node metastasis and overexpression of BMP7 (47.4%, P=0.005), CALD1 (42.1%, P=0.020), CDH1 (52.6%, P=0.001), COL3A1 (42.1%, P=0.020), EGFR (47.4%, P=0.005), ERBB3 (57.9%, P=0.000), PLEK2 (47.4%, P=0.024), and TCF4 (52.6%, P=0.001)." (PMID 34527572, 2021).
multiple sclerosis (2 papers, 2017 to 2019). A progressive autoimmune disorder affecting the central nervous system resulting in demyelination. "TCF4 is the potential transcription factor mediates Wnt signaling pathway that associated with infiltration of immune cells in multiple sclerosis." (PMID 31484947, 2019). "It has been reported that Tcf4 is expressed during remyelination stages in patients with multiple sclerosis and in the cuprizone mouse model of myelin loss, thereby supporting a role for Tcf4 in remyelination." (PMID 28912499, 2017).
myocardial infarct (2 papers, 2024 to 2025). "Enhancing the Wnt/β-catenin/TCF4 pathway can increase arrhythmia susceptibility by suppressing Nav1.5 expression, leading to arrhythmias during the acute phase of myocardial infarction (MI), while chronic remodeling occurs in later phases." (PMID 39482911, 2025).
myotonic dystrophy type 1 (2 papers, 2018 to 2020). Steinert disease, also known as myotonic dystrophy type 1, is a muscle disease characterized by myotonia and by multiorgan damage that combines various degrees of muscle weakness, arrhythmia and/or cardiac conduction disorders, cataract, endocrine damage, sleep disorders and baldness. "Based on other TNR diseases such as myotonic dystrophy type 1 (DM1), the prevailing view is that the triplet expansion in TCF4 produces the expression of toxic RNA resulting in discrete nuclear RNA foci that sequester the mRNA splicing factor, MBN1." (PMID 33099215, 2020).
Neurodevelopmental delay (2 papers, 2012 to 2024). "The phenotypic spectrum of TCF4 has, however, since been expanded to include neurodevelopmental delay in the absence of classical PHS." (PMID 38685113, 2024).
papillary thyroid carcinoma (2 papers, 2011 to 2022). "The localization of TCF-4 and TTF-1 in the same area of PTC tissues might be of clinical relevance, and justifies further examination of these factors in the papillary thyroid cancers follow-up." (PMID 21814573, 2011). "Finally, the localization of TCF-4 and TTF-1 in the same area of PTC tissues might also be of clinical interest, and justifies further examination of these factors in the follow-up of papillary thyroid cancer." (PMID 21814573, 2011).
prostate tumor (2 papers, 2005 to 2022). "Deregulation of CRT by HOXB13 results from the downregulation of TCF4 transcription factors, although aberrant activation of CRT pathway is seen in only small fractions of prostate tumours." (PMID 15928669, 2005).
psoriasis (2 papers, 2018 to 2024). An autoimmune condition characterized by red, well-delineated plaques with silvery scales that are usually on the extensor surfaces and scalp. "Indeed, a motif known to interact with TCF4 (5’-CAGGTG/CACCTG-3’) was more abundant in the 2 kb promoter region of the 191 IL17C-correlated genes as compared with all other genes expression in lesional skin of patients with psoriasis (PP) (P = 5.40 × 10–9, FDR = 1.47 × 10–6)." (PMID 38470486, 2024). "Finally, an identical Tcf4 targeting was also used to rule out the involvement of pDCs in an experimental model of psoriasis, and we now extend these observations to genetic models of IBD." (PMID 30410494, 2018).
triple-negative breast carcinoma (2 papers, 2014 to 2019). An invasive breast carcinoma which is negative for expression of estrogen receptor (ER), progesterone receptor (PR), and human epidermal growth factor receptor 2 (HER2). "We have also shown that β-catenin/TCF4-mediated p68 regulation plays an important function in enhanced expression of EMT marker proteins in triple-negative breast cancer cells MDA-MB 231, as well as in mouse 4T1 cells." (PMID 25499975, 2014).
abortion (1 paper, 2023). the ending of pregnancy by removing a fetus or embryo before it can survive outside the uterus. "Both STAT3 and TCF4 are downregulated in the decidua of patients with recurrent spontaneous abortion compared with those with normal pregnancy." (PMID 36982674, 2023).
age-related macular degeneration (1 paper, 2012). Age-related loss of vision in the central portion of the retina (macula), secondary to retinal degeneration. "Such a risk score is already in practice for age-related macular degeneration, a common retinal disease with confirmed susceptibility loci that show large effect sizes similar to TCF4 and in aggregate yield receiver operator curves with areas under the curve greater than 80%." (PMID 23110055, 2012).
astrocytoma (1 paper, 2019). "A positive correlation was also found between the expression level of TCF4 and LEF1 compared to the astrocytoma grade." (PMID 30468298, 2019).
Ataxia (1 paper, 2022). Ataxia refers to impaired coordination of voluntary muscle movement. "Interestingly, among two patients with TCF4 mutation, one showed dystonia only and other represented ataxia and myoclonus." (PMID 35719373, 2022).
basal cell carcinoma (1 paper, 2019). A carcinoma involving the basal cells. "For example, TCF7L2 (also known as TCF-4) from the basal cell carcinoma pathway plays a role in HIV latency maintenance and was up-regulated in the bystander model in our study." (PMID 31710657, 2019).
benign prostate hyperplasia (1 paper, 2019). "Furthermore, metastatic CaP was found to express higher levels of TCF4 and PTHrP (respectively) when compared to localized CaP and benign prostate hyperplasia." (PMID 31536510, 2019).
cardiomyopathy (1 paper, 2024). A disease of the heart muscle or myocardium proper. "Comparison of the regulon activity between HCM and NC identified activation of transcription factors (TFs) in HCM including KLF5 which was associated with cardiomyopathy,21, 22ETV1 which is involved in atrial remodelling, and TCF4 which participates in the WNT signalling pathway." (PMID 37766635, 2024).
cataract (1 paper, 2024). Partial or complete opacity of the crystalline lens of one or both eyes that decreases visual acuity and eventually results in blindness. "Follow-up analysis of the shared loci implicates candidate genes QKI, STK17A, TYR, NSF, and TCF4 likely contribute to the pathophysiology of cataracts and hearing difficulties." (PMID 38632618, 2024).
chronic lymphocytic leukemia (1 paper, 2021). "Interestingly we were able to identify a cluster of B cells expressing high level of TCF4 that was specific to the blood of patient 8, a patient suffering from chronic lymphocytic leukemia (CLL)." (PMID 33674591, 2021).
deafness (1 paper, 2025). An inherited or acquired condition characterized by the complete loss of the ability to hear from one or both ears. "In addition to GAPDH and TCF4, SLC4A11 was chosen as a comparison gene because of its confirmed association with congenital hereditary endothelial dystrophy (CHED) accompanied by perceptive deafness." (PMID 40244234, 2025).
dominant retinitis pigmentosa (1 paper, 2016). "Of which, three variants (ATXN1:NM_000332:p.E357K, TCF4:NM_001243226:c.1793-5G > A and KRT3:NM_057088:c.1189-5T > C) are known pathogenic variants of dominant retinitis pigmentosa." (PMID 27391953, 2016).
Epileptic encephalopathy (1 paper, 2025). A condition in which epileptiform abnormalities are believed to contribute to the progressive disturbance in cerebral function. "Representative examples include POLR1C (RNA polymerase dysfunction), TCF4 (Pitt–Hopkins syndrome), and HNRNPU (epileptic encephalopathy)." (PMID 41300846, 2025).
Failure to thrive (1 paper, 2025). Failure to thrive (FTT) refers to a child whose physical growth is substantially below the norm.
folate deficiency (1 paper, 2021). A nutritional condition produced by a deficiency of FOLIC ACID in the diet. "Since it has been confirmed that TCF4 plays a pivotal role in the activation of Wnt/β-catenin pathway, we also performed Co-IP assay between Gcm1 and TCF4 in folate deficiency." (PMID 33664222, 2021). "Overall these data indicated that the Gcm1/β-catenin/TCF4 tri-complex bound to Wnt target genes in folate deficiency, in which Gcm1 had specifically linked to Wnt target promoters." (PMID 33664222, 2021). "The results confirmed a detectable increased in the binding between β-catenin and TCF4 in folate deficiency." (PMID 33664222, 2021). "The results showed an increase in binding between Gcm1 and TCF4 in folate deficiency." (PMID 33664222, 2021).